CD4 (CD4 molecule)
Diseases named in the same sentence as CD4 in open-access papers (continued):
Sharing a sentence is not in itself a finding about the gene and the disease.
infection (continued). "After entering the human body, HIV infects cells by utilizing CD4 and CCR5/CXCR4 as primary and secondary receptors, respectively, leading to infection in its primary target cells such as T cells, macrophages, and dendritic cells, thereby establishing a long-term infection." (PMID 38785555, 2024). "In addition, patients who developed culture-positive infections had high CD52 MFI in CD4+ T cells than patients who were culture-negative, the CD52 MFI in CD4+ T cells was also correlated with serum C-reaction protein (CRP)." (PMID 39276679, 2024). "However, both CD4+ and CD8+ T cells appear to play a role in immunity to C. burnetii as immunodeficient mice lacking T cells reconstituted with either CD4+ or CD8+ T cells can control infection." (PMID 38567021, 2024). "Recent studies by the same group suggest that a loss-of-function mutation in CARD8, rendering it uncleavable by SIV in sooty mangabeys, might explain why they do not experience CD4+ T cell depletion after infection." (PMID 38785555, 2024). "Breakthrough infections occurred more frequently among previously non-infected individuals, who had significantly lower vaccine-induced spike-specific neutralizing activity and CD4 T cell levels." (PMID 38594497, 2024). "CT serovar D shedding is detected for only 10 days in immunologically normal mice after vaginal inoculation, and the infection course is unaltered in mice lacking CD4 T cells suggesting CT delivered intravaginally is insufficient for assessing adaptive immune responses." (PMID 39043447, 2024). "We next compared the numbers of NKG2D+CD4+ T cells before and after Lpn challenge to determine whether CD4+ TIA cells are already present in the lung before challenge or actively recruited to the site of infection." (PMID 38838013, 2024). "Similarly, in mouse models of Bacillus Calmette–Guerin (BCG) infection, IFN-γ-mediated depletion of antigen-specific CD4+ T cells has also been characterized, demonstrating a possible role of continued IFN-γ responses as a mechanism for infection-mediated T-cell apoptosis." (PMID 39132440, 2024). "Regarding infection, the more susceptible cells upregulated the expression of CCR5 but not CD4." (PMID 39372920, 2024). "The percentage of IFN-γ producing CD4+ and CD8+ T cells was calculated after stimulation with IE-1, pp65, gB, and gHgLpUL128L peptide pools in pregnant women with HCMV primary infection at an early and a late time point and in control subjects with HCMV remote infection." (PMID 39336935, 2024). "Moreover, while IFNγ produced by conventional CD4 T memory cells that expand early during infection can dampen CMV persistence, this is not sufficient to fully curtail replication." (PMID 38236791, 2024). "In the case of MARCH2, one previous report showed that it can inhibit infection in Jurkat cells, a T cell stable line, but it is well established that stable cell lines do not always reflect what happens in primary cells such as CD4+ T cells and MDMs." (PMID 39074162, 2024). "CD4 polyfunctional responses did not significantly increase after infection." (PMID 39260039, 2024). "Whilst CD4+ T-cell depletion led to an earlier loss of the WC1+ γδ T-cell population compared to the mock-depleted sheep, CD8+ T-cell depletion resulted in no loss of this population during peak infection." (PMID 38357545, 2024). "While the LTα level might contribute to susceptibility to acquisition, it does not appear to be through induction of mucosal-activated CD4+ T cells as targets of infection." (PMID 39438480, 2024). "Moreover, GFP expression was essentially absent in cells exposed to HIV-1 BaL-GFP in the presence of the reverse transcriptase inhibitor AZT, thus, demonstrating the specificity of detected GFP expression as a marker for de novo infection of both CD14+ cells and CD4+ T cells." (PMID 39872519, 2024).
infection (continued). "Apart from quantitative analyses, spike-specific CD4 and CD8 T cells were further characterized phenotypically for their expression of CTLA-4, which has been shown to be upregulated on antigen-specific T cells in response to recent antigen encounter during infections or vaccinations." (PMID 38594497, 2024). "Finally, the key role of macrophages in HIV-1 pathogenesis has been also demonstrated in HIV-1-infected humanized mice expressing only myeloid cells, where macrophages were sufficient to sustain productive infection in vivo, independent of CD4+ T cells." (PMID 38400063, 2024). "The percentage of IFN-γ producing CD4+ and CD8+ T cells showing a terminally differentiated effector memory phenotype (CD45RA+) remained constant in pregnant women with primary infection at the early and the late time points and in subjects with remote infection." (PMID 39336935, 2024). "On the contrary, there was a significant reduction in theeffector memory CD4+ T cells population in pulmonary compartment post SIVco-infection that cART + 3HP did not alleviate as was also seen in cART treated RMs.CD4+ TEM cells are critical for host protection to subsequentantigen encounter." (PMID 39257997, 2024). "In addition, we also detected robust IFN-γ production in CD4+ T cells upon heterologous challenge in vivo, where previous studies were limited to in vitro settings without prior infection." (PMID 38838013, 2024). "Thus, while increases in virus-specific CD4+ T cells lead to declines in viral load in all models, increases in virus-specific CD8+ T cells only impact viral loads in the models that include their role in infection clearance." (PMID 39575237, 2024). "On the other hand, we observed an increase in the activation of CD4+ T cells for the S and BA.1 stimulus between the pre-immune visit and the 2nd dose + 4 weeks, and between 2nd dose + 4 weeks to 2 to 8 weeks post-infection visit, but this result was not statistically significant." (PMID 38812507, 2024). "Proliferating Ki67+ CD4+ T cells can be detected in the tracheobronchial lymph nodes (TBLN) of experimentally infected pigs as early as 4 days after infection, and IFN-γ secreting CD8+ T cells can migrate to the lungs and bronchioalveolar lavage (BAL) by 6 days after infection." (PMID 38633745, 2024). "Thus, while CD40L-CD40 is not essential for the early CD4+ cell-dependent accumulation and activation of B cells during infection, these data implicate CD40-CD40L interactions as the mechanism by which CD4+ cells contribute to pan-B cell maintenance and BRM generation in the lung." (PMID 38715601, 2024). "Interestingly, however, when stratified for individuals with and without prior infection correlation patterns of CD4 and CD8 T cells with humoral immune response parameters showed some distinct differences that were unmasked by combined analysis." (PMID 38594497, 2024). "After 40 days of infection, clonal expansion could still be observed in the CD4+ effector, but not the CD8 central memory populations." (PMID 37325645, 2023). "Similarly, both consensus and autologous Tat-mediated transcriptional activity of the T/F LTR variants show a significant positive correlation with viral load but negative correlation with CD4 T cell count at one-year post infection." (PMID 37307292, 2023). "We further assessed frequencies of circulating T follicular helper (cTfh) populations, memory CD4+ T cells critically involved in providing B cell help in infection and vaccination, from the PBMCs of non-infected and S. mansoni-infected individuals by flow cytometry." (PMID 37406029, 2023). "Moreover, studies highlight the essential role of CD4+ Tfh in HIV reservoir formation and maintenance, so their activation might enhance infection." (PMID 37883584, 2023). "It is however noteworthy that CD4+ T cells did not expand at any time post-infection, supporting the hypothesis that CD8+ T cell depletion occurs during BTV acute infection." (PMID 37920474, 2023).
infection (continued). "Our findings of the regulation of immune protein expression after GBS infection within the chorion and decidua may be important in understanding how decidual CD4+ and CD8+ T cells balance the role of preventing an allogeneic response against the fetus while protecting against infection." (PMID 38239507, 2023). "We noticed that CD4+ T cell-depleted, CD8+ T cell-depleted, and isotype control animals challenged with H99 cells maintained or increased body weight over time, while the CD4+ and CD8+ T cell double-depleted mice and unvaccinated ones lost weight rapidly following infection." (PMID 36719231, 2023). "Therefore, HIV-1 uses moesin and filamin-A to promote the aggregation of HIV-1 receptors in a pole of the cell, thereby regulating CD4/CXCR4-CCR5 diffusion at the cell surface in an actin cytoskeleton-dependent manner to facilitate the first events of the infection process." (PMID 37685911, 2023). "Herein, neither FoxP3 expression by CD3highCD4+ T-cells nor the tTreg frequency changed upon in vitro HIV infection alone or in combination with TGF-β1 treatment, suggesting that thymocyte infection with HIV does not affect FoxP3 expression by CD4 T-cells or tTreg differentiation." (PMID 37547675, 2023). "These interactions may function as receptors of attachment in order to facilitate the infection of target cells negative for CD4 and/or CCR5/CXCR4 coreceptors that are normally responsible for viral entry." (PMID 37511488, 2023). "In inactivated vaccine-healthy individuals, the memory T cell responses to BA.1 and BA.4/5, including CD4+ helper subsets, CD4+ memory subsets, CD8+ memory subsets, the polyfunctional profiles of CD4+ T cell and CD8+ T cell, were similar with the pattern in breakthrough infection individuals." (PMID 37037791, 2023). "Similarly, another report also suggested that infection biomarkers, such as procalcitonin, were significantly increased, and the absolute counts of CD3+, CD4+, CD8+ T cells, and NK cells were significantly reduced in severe HAdV infection patients compared with mild patients." (PMID 36732702, 2023). "Furthermore, VZV infection of MAIT cells was less than that of infection of ARPE-19 cells but comparable to infection of non-MAIT cell CD4+ and CD8+ T lymphocyte populations." (PMID 37006246, 2023). "In addition, we found a significant negative association with CD4+ TEM, CD4+ TTM, and CD8+ TN activation but a positive association with CD4+ TN and CD4+ TCM activation post-infection in the BBIBP-CorV group." (PMID 38140668, 2023). "Infection-mediated nanotubes could be established between T CD4+ lymphocytes (infected and noninfected pairs) or between T CD4+ lymphocytes and dendritic cells (DCs)." (PMID 37685911, 2023). "However, such approaches would require determining the extent of sufficient protection from infection via a memory CD4 T cell compartment, when antibodies are no longer detectable and when antibody epitopes have undergone mutations." (PMID 37313411, 2023). "In this matter, during the infection of DCs, HIV-1 (which enters the cell using the lectin DC-SIGN) mediates the activation of a GTPase and the remodeling of the actin cytoskeleton to promote filopodia extension that allows virus transmission to neighboring CD4+ T cells." (PMID 37685911, 2023). "Therefore, while we have not fully characterized the CD4+ T cell subtypes following infection, it is possible that CVB3 also drives a predominantly Th2 response, limiting inflammation in our model." (PMID 38274806, 2023). "Our model takes advantage of this fact, as we show here that Eomes is not induced in CD4+ T cells during the acute phase after LCMV WE infection and therefore all effects observed in T cells carrying the Tbx21E allele can be ascribed to the actions of the Tbx21E allele." (PMID 36756120, 2023).
infection (continued). "High % of seropositivity at baseline.HPV-16 and HPV-18 antibody titers remained above levels associated with natural infection at 12 months.Vaccination resulted in sustained HPV-16 and HPV-18 CD4 T-cell responses.No impact of baseline CD4 count or HIV VL on the magnitude of the immune response." (PMID 37376456, 2023). "However, the absence of CD4 or CD8 lymphocytes did not prove critical, and animals with this deficiency recovered from infection." (PMID 37454101, 2023). "Thus, after a primary HIV infection, a small number of CD4+ memory T cells are infected by the virus (unlike the rest of the CD4 cells, which are rapidly destroyed after infection) and establish a reservoir." (PMID 36839593, 2023). "Similarly, HIV/SIV enters the CNS within 2 weeks post-infection, primarily via infected CD4+ T cells and monocytes/macrophages that transport the virus across the blood brain barrier (BBB) and facilitate infection of CNS resident cells, perivascular macrophages, and microglia." (PMID 36890518, 2023). "While depletion of CD4 T-cells alone did not significantly impact the progression of MA-CCHFV infection nor did it have an impact on viral loads in male mice, in male mice depletion of both CD4+ and CD8+ T-cells further worsened disease compared to just CD8 depletion alone." (PMID 37866114, 2023). "Although these products were not genetically modified to resist infection, it is unlikely that direct infection of the low percentage of CD4+ CE-XTC in each infused product contributed to the low frequency of infused cells in the blood or lack of protection against mucosal SHIV challenge." (PMID 37207227, 2023). "In the second host, recovery of almost all donor-derived memory required infection with IAV expressing the peptide seen by the TCR transgenic effector CD4 T cells, but could not be induced by IAV lacking that epitope." (PMID 38152398, 2023). "Second limitation was lack of kinetic analysis of IFN-γ CD4+T cell responses in individuals with full follow-up for 1–2 years after infection, which potentially could have explained the development and persistence of cellular immunity against DBPII." (PMID 37173361, 2023). "With this infant-trained model, we show that sequence diversity accumulates with time for most infants and that the rate of this accumulation varies by individual, gene-region, and mode of infection, but not by set-point viral load or rate of CD4+ T cell decline." (PMID 38117834, 2023). "Thus, the origin of the subtype-specific difference in the CD4+ T cell level after primary infection is not clear yet." (PMID 37161335, 2023). "We could not determine a direct link between CD4+-T-cell levels and infections in general in the setting of CD4+-T-cell-guided anti-infective prophylaxis strategies." (PMID 37152008, 2023). "The proportions of activated CD4+ T cells after the first dose of vaccine in 11 children previously uninfected tended to be higher than responses to prevaccination infection in 11 children (median, 0.07% vs 0.04%), without reaching statistical significance (P = .08)." (PMID 38107018, 2023). "These interactions may function as receptors of attachment in order to facilitate infection of CD4 low or negative cells or promote interactions with other receptors leading to the activation of signaling pathways or pathogenesis." (PMID 37511488, 2023). "We demonstrated that Tcra−/− mice that received CnH99 (100 yeasts, i.n.)preinfection and CD4+ T cell (106 cells, i.v.)transfer (C-IRIS condition) also had a significantly higher mortality rate than that of control mice (naive, CD4+ T cell transfer alone, CnH99 infection alone)." (PMID 37380639, 2023). "Results indicated that the number of CD8+ T cells decreased significantly by about 50% at 4 dpi (253.74 ± 178.58, P = 0.0427) compared to uninfected baseline (day 0, 574.37 ± 241.20), then increased sharply, while the number of CD4+ T cells showed nonsignificant changes during infection." (PMID 37033979, 2023).
infection (continued). "In the context of a therapeutic vaccine, the use of epitopes identified with this system may allow the generation of a broader CD4+ T cell response including epitopes that were not targeted by the initial response to infection in PLWH." (PMID 37058141, 2023). "However, neither PD-1 blocked CD4+ T cell-depleted mice nor μMT animals had exacerbated infection, demonstrating this effect is both CD4+T and B cell dependent." (PMID 37721965, 2023). "Therefore, while HIV-specific CD4+ CTL may be targeted by the virus and experience depletion during the early stages of infection, the remaining cells might play an important role in controlling viral loads." (PMID 37965314, 2023). "Astonishingly, no infection was detected in our study, which could be owed to the CD4 count greater than 200 cells/mm3, the undetectable viral load, and well-comprehensive perioperative management." (PMID 38057748, 2023). "In contrast, IN-2 was found in the cytoplasmic compartment and in the induced NEIs in HIV-89.6-EGFP-infected cells, suggesting that loading of late endosomes with viral components is important for these processes in CD4+ T cells, which are devoid of NEIs without infection." (PMID 37563144, 2023). "Productive HSV-2 infection of activated CD4+ T cells was confirmed using a low-passage clinical isolate, HSV-2(SD90), at MOI = 0.001 and quantification of infectious virus released into culture supernatants at 6, 24, and 48 hours post-infection (hpi) by plaque assay." (PMID 37079384, 2023). "Therefore, CD4 and CD8 genes are up-regulated in the immune-related tissues of the juvenile M. amblycephala post infection, which might interact with MHC class II or I molecule and play an important role in the immune response." (PMID 36969197, 2023). "However, at the onset of infection, innate immune cells such as dendritic cells, NK cells, NKT cells, Υδ T cells and B1 cells macrophage/monocytes respond to infection and also induce the cells of the adaptive immune system, the CD4+ and CD8+ T lymphocytes." (PMID 37408185, 2023). "Even at the site of infection, CD4+ T cells do not have an abundant profile." (PMID 38140266, 2023). "Indeed, early CD4+ T cell depletion would result in viral persistence, whereas no impact on infection course was demonstrated for CD4+ T cell depletions obtained six weeks after inoculation." (PMID 37108816, 2023). "However, reactive CD4+ T cell frequencies as well as IgG and serum ID50 titers in both D– and D+ patients were higher than those observed in convalescent patients after mild infection, and interestingly also compared with the double-vaccinated controls." (PMID 36881474, 2023). "In addition, treatment of septic animals with HCEPg induced an increase in the CD4+ CD69+ T lymphocyte population, which is impaired in septic pictures with the significant reduction in the number of CD4 T cells, which affects the host response to infection." (PMID 37621924, 2023). "Thus, while animals deficient in B cells and CD8 T cells are able to control ABLV‐luc infection and survive long‐term in response to F11 therapy, mice lacking a functional CD4 T cell compartment are not." (PMID 37767784, 2023). "Recombinant IL-6 did not increase infection level in activated CD4 + T cells." (PMID 37202790, 2023). "Nine vaccine recipients without evidence of prior infection and paired samples showed significant increases in CD4+ T-cell activation by expression of CD69 and CD137 in response to spike peptide pool stimulation after subtraction of the unstimulated control (median difference, 0.04%; P = .04)." (PMID 38107018, 2023). "Instead, we hypothesized that most Nur77-GFPLO CD44+ CD4 T cell population are Mtb-specific effector cells expanded upon infection, but that have not recently been activated at the time of the harvest." (PMID 38110410, 2023). "However, the CD4+/CD8+ T cell ratio increased in the Ts65Dn mice along rhRSV-Luc infection but not in wild type mice." (PMID 37112973, 2023).